ZNF337 (zinc finger protein 337)
Description:
May be involved in transcriptional regulation.
Synonyms: dJ694B14.1
Tractability: Antibody: the Human Protein Atlas places it where antibodies can reach. PROTAC: UniProt records ubiquitination sites on it; ubiquitination databases record sites on it.
Gene: Protein-coding gene on chromosome 20 (25,673,195 to 25,696,860, reverse strand). Ensembl gene ENSG00000130684.
Subcellular location: Nucleus
Subcellular location (Human Protein Atlas): Plasma membrane; Nuclear speckles
Pathways (Reactome):
Gene expression (Transcription): Generic Transcription Pathway
Gene Ontology:
Molecular function: protein binding; DNA-binding transcription factor activity, RNA polymerase II-specific; RNA polymerase II transcription regulatory region sequence-specific DNA binding; sequence-specific DNA binding
Biological process: regulation of transcription by RNA polymerase II; regulation of DNA-templated transcription
Cellular component: nucleus
Genetic constraint (gnomAD): Loss-of-function variants: 8 observed, 13.3 expected, observed/expected ratio (o/e) 0.6, 90% interval 0.35 to 1.09. The upper end of that interval is the gene's LOEUF score, 1.09, which puts it in group 4 of 6, group 1 being the genes least tolerant of losing a copy. Missense variants: 882 observed, 945.13 expected, observed/expected ratio (o/e) 0.93, 90% interval 0.88 to 0.99. Synonymous variants: 336 observed, 335.72 expected, observed/expected ratio (o/e) 1, 90% interval 0.92 to 1.1.
Homologues: Orthologues: chimpanzee ZNF337 (99% identical), macaque ZNF337 (50% identical), mouse Zfp78 (23% identical), Drosophila melanogaster CG2712 (17% identical), Drosophila melanogaster CG3281 (17% identical), Drosophila melanogaster Phs (15% identical). Paralogues in human: ZNF875 (40% identical), ZNF133 (39% identical), ZNF343 (36% identical), ZNF169 (36% identical), PRDM9 (30% identical), ZNF425 (27% identical), ZNF25 (27% identical), ZFP90 (26% identical), ZNF614 (26% identical), ZNF805 (26% identical), ZFP37 (26% identical), ZNF266 (26% identical), and 50 more.
Diseases named in the same sentence as ZNF337 in open-access papers:
ZNF337 is named in the same sentence as 6 diseases in open-access papers, as found by Europe PMC text mining. Sharing a sentence is not in itself a finding about the gene and the disease. The quoted sentences say what the papers report.
breast neoplasm (1 paper, 2021). A benign or malignant neoplasm of the breast parenchyma. "The current investigation suggests future assessment of the functional role of APTR, AC144450.1 and ZNF337.AS1 in the development of breast neoplasms." (PMID 34094972, 2021).
colon cancer (1 paper, 2023). "There was no information of the expression of ZNF337 in READ on the HPA database, so we identified the expression of ZNF337 in colon cancer instead." (PMID 36879254, 2023).
rectal cancer (1 paper, 2023). A primary or metastatic malignant neoplasm that affects the rectum. "Future articles in this series will go into more details about the effects of hub genes of PLAGL2, ZNF337 and ALG10 on the phenotype of rectal cancer cells after irradiation in vitro and in vivo." (PMID 36879254, 2023).
cancer (1 paper, 2023). A tumor composed of atypical neoplastic, often pleomorphic cells that invade other tissues. "ZNF337, named as zinc finger protein 337, encodes a zinc finger domain containing protein and its biological function has yet to be determined and the role in tumorigenesis and cancer progression are still unclear." (PMID 36879254, 2023).
tumor (1 paper, 2023). "A nomogram was constructed using the TCGA READ dataset based on the expression of ALG10, PLAGL2 and ZNF337 and the clinical characteristics including age, gender, stage, tumor (T), lymph node (N) and metastasis (M) stage." (PMID 36879254, 2023). "Analysis based on exploration of the clinical predictive value showed PLAGL2, ZNF337 and ALG10 were significantly associated with tumor immune infiltration, different immune-related genes and sensitivity of chemotherapeutic drugs." (PMID 36879254, 2023).
ZNF337 also shares sentences with these, for which no sentence is quoted: infection (1 paper).